GFAP (glial fibrillary acidic protein)
Diseases named in the same sentence as GFAP in open-access papers (continued):
Sharing a sentence is not in itself a finding about the gene and the disease.
injury (continued). "Interestingly, these players had elevations of either GFAP or NFL, suggesting that these are tracking different aspects of brain injury." (PMID 33543129, 2020). "Consistent with earlier studies, the increased APP, GFAP and BMX metabolites are observed following brain injury using similar Marmarou acceleration weight drop model or other experimental TBI models, such as controlled cortical impact or fluid percussion models of brain injury." (PMID 28552947, 2017). "GFAP levels peak at 1–2 days following severe brain trauma, and are normal in patients with other trauma that does not include traumatic brain injury, an indication of GFAP's brain specificity." (PMID 27468268, 2016). "In particular, early biomarkers of structural damage, such as S-100B, GFAP, and UCH-L1 may be used to assist physicians in assessing a brain injury and determining whether to order a head CT scan for patient with a mild TBI." (PMID 26016501, 2015). "Thus, measuring VEGF, GFAP, and IL-10 soon after admission to the NICU may assist to stratify more accurately moderate–severe HI brain injury." (PMID 34795631, 2021). "Although increases in interleukin (IL)-6, IL-8, IL-10 and glial fibrillary acidic protein (GFAP) were observed in FGR infants with brain injury, it is not clear whether similar increases would be observed in cases of more subtle brain injury in FGR infants that are not currently detectable at birth." (PMID 38966491, 2024).
ependymoma (49 papers, 2006 to 2025). A WHO grade II, slow growing tumor of children and young adults, usually located intraventricularly. "It has been reported that the GFAP expression correlates with a loss of E-cadherin expression in anaplastic ependymomas, although in this case there was E-cadherin expression." (PMID 32612806, 2019). "In the well-circumscribed regions of the ependymoma, the tumor exhibited the typical features of ST-ZFTA ependymoma, with GFAP staining showing a diffuse fibrillary background in low-cellularity areas." (PMID 41464145, 2025). "These areas are morphologically very similar to subependymomas, which are benign GFAP-rich tumors, raising the idea of a morphological spectrum between subependymoma and ependymoma." (PMID 41464145, 2025). "Immunohistochemically, ependymomas arising in other locations, are characterized by positivity for GFAP, negativity for OLIG2, and dot-like or ring-like cytoplasmic positivity for EMA." (PMID 38544524, 2024). "Ependymomas test positive for glial fibrillary acidic protein (GFAP), epithelial membrane antigen (EMA), S-100, and vimentin on immunohistochemistry." (PMID 39293224, 2024). "The ependymoma‐like tumor cells were immunoreactive for GFAP, with perivascular cytoplasmic processes having particularly strong staining." (PMID 33576087, 2021). "Based on morphological and immunohistochemical characteristics of tumor cells that expressed glial fibrillary acidic protein (GFAP), S-100, and vimentin, the tumor was diagnosed as an ependymoma." (PMID 34716641, 2021). "Ependymomas with tanycytic histology displayed round to oval, mostly isomorphic cell nuclei and elongated cell processes, particularly highlighted by GFAP immunostaining." (PMID 33481105, 2021). "Glial fibrillary acidic protein can differentiate these tumors from the ependymoma, which is the most common differential diagnosis." (PMID 34307231, 2021). "All ependymomas were positively stained with GFAP and at least focally with EMA (dot-like/ring-like staining)." (PMID 33925821, 2021). "Where immunohistochemistry staining was available for review, the typical ependymoma profile with GFAP and EMA dot-like positivity was seen." (PMID 32641156, 2020). "Similar to human ependymomas, there was consistent extensive immunopositivity for the glial marker GFAP detected in the mouse tumor cells." (PMID 33228790, 2020). "Inside the list of proteins identified by top-down approach, a separate discussion was devoted to the diverse peptide fragments of GFAP and vimentin and of their citrullinated forms naturally occurring in the ependymoma tissue intact proteome." (PMID 32183175, 2020). "Histological re-evaluation in five primary tumors and seven relapses showed characteristic histological features of ependymoma, namely pseudorosettes, GFAP- and EMA positivity." (PMID 31414211, 2019). "Immunohistochemically, ependymomas are characterized by a diffuse expression of GFAP and S-100 protein and can also express epithelial markers such as EMA." (PMID 28088216, 2017). "Glial-derived tumors are classified based on histologic subtype, which include glial fibrillary acidic protein positive (GFAP+) astrocytic tumors, oligodendrogliomas, ependymomas and a mixture of the subtypes." (PMID 27057463, 2016). "The pathologic diagnosis of ependymoma is based on H&E histologic examination and confirmation of the neoplastic origin by glial fibrillary acidic protein IHC." (PMID 25775275, 2015). "Dot-like EMA positivity and GFAP positivity particularly in the perivascular zone observed in ependymomas are helpful markers in differentiating oligodendrogliomas from clear cell ependymomas." (PMID 24744929, 2014). "With positive immunohistochemical staining for GFAP, this cellular pattern is quite characteristic of an ependymoma." (PMID 24963425, 2014).
ependymoma (continued). "Immunohistochemical staining of the permanent section revealed strong immunoreactivity for glial fibrillary acidic protein with intermittent S-100 positivity, confirming that the tumor was a tanycytic ependymoma." (PMID 23476839, 2013). "Additionally, exploring similarities in IHC staining, both PLNTY and ependymoma are known to stain positive for GFAP." (PMID 39582680, 2024). "EET MN1-BEND2 express high mRNA levels of the ependymoma-associated genes FOXJ1, IGF2, CELSR1, RFX3, KCNJ5, TFF3 and YAP1 and relatively low levels of messages of canonical astrocyte marker genes such as OLIG2, GFAP, ALDH1L1, and S100 β." (PMID 36604386, 2023). "In addition, a myxopapillary ependymoma is known to express the glial fibrillary acidic protein (GFAP)." (PMID 34203272, 2021). "Ependymomas may show a similar immunohistochemical pattern, but GFAP immunoactivity in ependymomas is often more intense than that in astroblastomas." (PMID 29678196, 2018). "Tanycytic ependymoma stains positive for GFAP and vimentin but rarely stains S-100." (PMID 23476839, 2013). "On the other hand, ependymomas could show different glial markers, specifically GFAP." (PMID 40677455, 2025). "However, a review of the literature on current genetic biomarkers and immunohistochemical staining reveals two commonalities between PLNTY and ependymoma: mutations in the histone gene H3F3A and positive Glial Fibrillary Acidic Protein (GFAP) staining on immunohistochemistry (IHC)." (PMID 39582680, 2024). "Therefore, we sorted out the ependymoma-derived CTCs expressing both Pan-CK and GFAP." (PMID 37046450, 2023). "Cellular HB may express GFAP, but intensity is weaker and less extensive than in ependymoma." (PMID 28320419, 2017). "The recent finding of positive GFAP staining in both PLNTY and ependymoma suggests another avenue for exploring possible links between these two CNS pathologies." (PMID 39582680, 2024). "Glial fibrillary acidic protein (GFAP) was positive, and epithelial membrane antigen (EMA) showed perinuclear dot-like positivity in a few cases of ependymoma." (PMID 39165459, 2024). "Immunohistochemistry should be performed for EMA or podoplanin, GFAP, BCOR, and p65-RELA or L1CAM for ZFTA-RELA ependymomas." (PMID 36604386, 2023). "In contrast to Ependymoma, paragangliomas located in the cauda equina region do not exhibit expression of GFAP and EMA." (PMID 40852478, 2025). "They exhibited similar ependymoma-like features or a microcystic pattern, along with focal or absent GFAP immunostaining, and shared the same DNA methylation profile." (PMID 38216991, 2024). "In contrast to the diffuse positivity typically observed in ependymomas, perivascular pseudorosettes were GFAP-negative." (PMID 38216991, 2024). "The ependymoma-like aspect coupled with the lack of diffuse GFAP immunostaining and the presence of OLIG2 positivity are useful clues for recognizing these tumors in histopathological practice." (PMID 38216991, 2024). "GFAP staining in ependymoma is common but usually not diffusely positive in all neoplastic cells, and it shows perivascular accentuation." (PMID 35885538, 2022). "Immunological staining with GFAP and vimentin is very helpful for the differential diagnosis of ependymomas from other non-ependymal tumors, such as astrocytic and choroid plexus tumors, and also in differentiating between the various grades of ependymomas." (PMID 32612806, 2019). "Histopathological evaluation of ependymoma tissue reveals pseudo-rosette formation, high mitotic activity, vascular proliferation and necrosis, EMA staining with perinuclear dot-like structures and with diffuse GFAP immunoreactivity." (PMID 32612806, 2019). "The immunohistochemical characteristics of PTPR include variable immunoreactivity for cytokeratin and S-100 protein, and complete absence of immunoreactivity for GFAP; therefore, GFAP staining aid in distinguishing this neoplasm from an ependymoma." (PMID 26622493, 2015).
ependymoma (continued). "Trisomy 19 ependymomas have an immunohistological profile of ependymal tumors: positive for glial fibrillary acidic protein (GFAP) and epithelial membrane antigen (EMA), and negative for neuronal markers." (PMID 17626628, 2007). "Further immunohistological examinations of paraffin embedded tissue sections indicated that the ependymoma was strongly stained for GFAP and S100 (data not shown)." (PMID 16948860, 2006). "Indeed, the cases histopathologically presented as “mixed subependymomas-ependymomas” with well-circumscribed tumors exhibiting a diffuse immunoreactivity for GFAP, without expression of Olig2 or SOX10." (PMID 38581034, 2024). "However, abundant perivascular pseudorosettes and GFAP-highlighted radial perivascular processes, the cardinal histologic features of ependymoma were not reproducibly observed." (PMID 33228790, 2020). "The expression of cytokeratin and transthyretin by tumor cells and the lack of GFAP expression differentiated this tumor from ependymoma, and the co-expression of cytokeratin, S-100 protein and vimentin with negative CEA was helpful in distinguishing it from metastatic carcinoma." (PMID 22752623, 2013). "Immunohistochemistry shows positivity for GFAP, negativity for OLIG2, and absence of dot-like EMA positivity, which instead characterizes other ependymomas." (PMID 38544524, 2024). "The presence of ependymal and perivascular rosettes, immunoreactivity for GFAP (although oligodenrogliomas may also by positive for GFAP) and absence of CD57 and CD99 expression can be helpful for the establishment of a diagnosis of ependymoma." (PMID 20849631, 2010).
Autoimmunity (48 papers, 2012 to 2026). The occurrence of an immune reaction against the organism's own cells or tissues. "Myelin oligodendrocyte glycoprotein (MOG) antibody-associated disease (MOGAD) and autoimmune glial fibrillary acidic protein (GFAP) astrocytopathy have received increasing attention in recent years." (PMID 41333477, 2025). "It is also possible that certain autoimmune diseases initiate primary inflammation and disrupt astrocytic function, whereas GFAP autoimmunity is associated with the secondary phenomenon." (PMID 38585352, 2024). "The potential differential diagnostic value is exemplified by the associations between elevated NfL levels and underlying autoimmune disorders, t-Tau and catatonia with features of excitation, and GFAP and prodromal infections." (PMID 39048548, 2024). "This study implies a connection between astrocytopathy and autoimmunity and high levels of GFAP linked to astrocytic lysis in pathology, with levels decreasing after immunotherapy." (PMID 39279053, 2024). "In 2016, Fang and Lennon first described GFAP-IgG, an antibody associated with autoimmune meningoencephalomyelitis, and unified the spectrum of diseases under the name of autoimmune GFAP astrocytopathy." (PMID 36552122, 2022). "Myelin oligodendrocyte glycoprotein (MOG) antibody-associated disease (MOGAD) and autoimmune glial fibrillary acidic protein (GFAP) astrocytopathy are demyelinating diseases of the central nervous system (CNS) that have received increasing attention in recent years." (PMID 41333477, 2025). "Only one patient had symptoms consistent with GFAP-associated autoimmunity." (PMID 36845122, 2023). "In addition, complement C4d activation might play a role in GFAP autoimmunity, either as cause or consequence of astrocytic reactivity." (PMID 38310187, 2024). "A 30-year-old Chinese male diagnosed with autoimmune glial fibrillary acidic protein (GFAP) astrocytopathy presented with cerebrospinal fluid (CSF) eosinophilia." (PMID 41142784, 2025). "Overall, the CSF cytokine profiles identified in GFAP‐IgG‐positive patients complement the CNS histopathological findings, inform the pathogenesis of GFAP autoimmunity, and suggest therapeutic targets." (PMID 39869499, 2025). "Necrotizing inflammation has been described in pug dogs with GFAP autoimmunity, while human histopathological studies revealed a lymphocytic and a granulomatous phenotype, potentially representing distinct pathomechanisms or disease stages." (PMID 39869499, 2025). "A murine model of GFAP‐specific CD8+ T‐cell autoimmunity revealed a spontaneous chronic relapsing–remitting course and a viral‐induced acute, monophasic course." (PMID 39869499, 2025). "Defining the CSF cytokine/chemokine and injury biomarker signature of glial fibrillary acidic protein (GFAP) autoimmunity can inform immunopathogenesis." (PMID 39869499, 2025). "Glial fibrillary acidic protein astrocytopathy is a rare autoimmune condition characterized by antibodies against glial fibrillary acidic protein in astrocytes of the central nervous system." (PMID 41497949, 2025). "Previous pathological studies of GFAP autoimmunity have shown neuronal injury in some study patients." (PMID 39869499, 2025). "CSF cytokine/chemokine findings in GFAP autoimmunity correlate with histopathology; GFAP and NfL hold promise as disease biomarkers." (PMID 39869499, 2025). "Our histopathological findings indicate that a cytotoxic T cell-mediated immune reaction is present in GFAP autoimmunity." (PMID 38310187, 2024). "No other signs of complement activation on astrocytes, such as the deposition of C1q and C5b-9 were detected in GFAP autoimmunity." (PMID 38310187, 2024). "The variables with the highest importance were Comorbid autoimmune disorder, Infectious prodrome, Catatonia symptoms for NfL, GFAP and t-Tau, respectively." (PMID 39048548, 2024).
Autoimmunity (continued). "Variable changes of AQP1 and AQP4 were found in biopsied CNS samples compared with normal controls reflecting the astrocytic reactions to stress within the context of GFAP autoimmunity." (PMID 38310187, 2024). "Patients with anti-GFAP antibodies are often complicated with infection, autoimmunity, hyponatremia, and pathological CSF." (PMID 37205100, 2023). "Some patients had a neoplasm detected and GFAP expressed by neoplasms is plausible as immunogen triggering paraneoplastic neurological autoimmunity." (PMID 37016352, 2023). "Subsequently, the presence of anti-GFAP antibodies was detected in the cerebrospinal fluid (CSF), and the diagnosis of autoimmune GFAP astrocytopathy in conjunction with low-flow PMAVFs was confirmed through spinal digital subtraction angiography (DSA)." (PMID 38111582, 2023). "Autoimmune glial fibrillary acidic protein (GFAP) astrocytopathy is a treatable autoimmune disorder affecting the central nervous system." (PMID 37781407, 2023). "CSF test showed GFAP-IgG positive, elevated WBC counts and protein, with low glucose and chlorine, while MRI showed a reversible lesion on SCC, leading us to diagnose autoimmune GFAP autocytopathy accompanied with RESLES." (PMID 37190624, 2023). "Here, we retrospectively summarize the clinical and auxiliary examination characteristics and prognosis of 15 Chinese patients to provide additional findings on GFAP autoimmunity." (PMID 36552122, 2022). "Positive serum or CSF GFAP-specific IgG antibodies are a specific indicator for the diagnosis of autoimmune GFAP astrocytosis." (PMID 36482607, 2022). "The clinical manifestations of GFAP autoimmunity are heterogeneous among different cohorts, possibly due to the small samples or the human species, and require further study." (PMID 36552122, 2022). "In patients with GFAP autoimmunity, presenting with a chronic relapsing course, one should actively search for immunogenic factors and the culprit antibodies." (PMID 36552122, 2022). "Antibodies in cerebrospinal fluid (CSF) against GFAP are biomarkers and expressed in most cases with autoimmune GFAP astrocytopathy." (PMID 34646641, 2021). "Further, this case highlights the importance of recognizing the role of peripheral nerve involvement in GFAP autoimmunity." (PMID 34160439, 2021). "Autoimmune glial fibrillary acidic protein astrocytopathy is a novel form of autoimmune meningoencephalitis related to GFAP autoantibodies." (PMID 33569363, 2020). "A new type of meningoencephalitis known as autoimmune glial fibrillary acidic protein (GFAP) astrocytopathy has been recently defined." (PMID 31921724, 2019). "Based on the literature, autoantibodies were also tested against six potential organ–specific antigens implicated in T1D and/or other autoimmune conditions including ATP4B, TGM2, TPO, KCNRG, AQP-4, and GFAP." (PMID 23028856, 2012). "This temporal relationship suggests that viral infection may have acted as a trigger or aggravating factor for GFAP autoimmunity, consistent with previous reports linking the disease to parainfectious or paraneoplastic phenomena." (PMID 41181139, 2025). "AQP4-IgG may initiate a primary inflammatory event and disrupt astrocytic function, while GFAP autoimmunity occurs as a secondary phenomenon." (PMID 39949796, 2025). "While most patients with GFAP autoimmunity respond well to glucocorticosteroids, this treatment is associated with various side effects, and a subset of patients relapse; IL6 pathway blockade could be considered in this population." (PMID 39869499, 2025). "While some antibodies are helpful for differential diagnosis, such as anti-aquaporin 4 (AQP4), primarily associated with neuromyelitis optica spectrum disorders (NMOSDs), glial fibrillary acidic protein (GFAP) antibodies are typically found in patients with autoimmune GFAP astrocytopathy." (PMID 39859557, 2025).